TNF (tumor necrosis factor)
Diseases named in the same sentence as TNF in open-access papers (continued):
Sharing a sentence is not in itself a finding about the gene and the disease.
inflammatory bone diseases (continued). "Tumor necrosis factor-α (TNF-α) is one of the most versatile cytokines, it is a product of the immune system secreted by macrophages, and its role in bone inflammatory diseases is well documented as pro-resorptive aiding in disease progression." (PMID 31921183, 2019). "We also observed that vaginal infection with GV results in elevated levels of TNF-α, IL-6, and RANKL, as well as an elevated number of NF-κB-positive cells in the vagina, femur, hippocampus, and hypothalamus, leading to vaginitis, osteitis, and neuroinflammation, as previously reported." (PMID 40284791, 2025). "Higher expression levels of inflammatory cytokines, such as IL-6, IL-11, and TNF-α, were identified more in the bone tissue obtained from CRS patients with osteitis than in those without osteitis." (PMID 33477617, 2021).
Kaposi's sarcoma (30 papers, 2009 to 2025). A malignant neoplasm characterized by a vascular proliferation which usually contains blunt endothelial cells. "In the C vs. SP comparison, it was determined that TNF, NFKB, and MAPK signaling pathways, along with transcriptional misregulation in cancer and Kaposi sarcoma-associated Epstein–Barr virus infection pathways, were significantly changed cancer-related pathways." (PMID 41472277, 2025). "The noted high degree of vascularization in Kaposi’s sarcoma may be one of the explanations for the high degree of success, given that TNF-alpha is known to induce vascular hemorrhage in malignant tissues." (PMID 30170620, 2018). "Angiostatin (AST) in an angiogenic setting using the matrigel sponge angiogenesis assay in C57bl mice effectively inhibited angiogenesis produced by inclusion of a potent angiogenic cocktails, either supernatants from Kaposi's sarcoma cells or a combination of VEGF and TNFα." (PMID 19144161, 2009).
ovarian tumor (30 papers, 2009 to 2024). "It has been demonstrated that Snx27 inhibits tumor necrosis factor alpha (TNFα)-induced NF-κB signaling activation by regulating the TNFα receptor complex associated with ovarian tumor (OTU) deubiquitinase with linear linkage specificity (OTULIN) and linear ubiquitination." (PMID 39494909, 2024). "A novel mouse model that utilizes transgenic female mice bearing ovarian tumors to study cancer cachexia.Notable biomarkers of this model are, growth differentiating factor 15, interleukin-6, interleukin-1 beta, and tumor necrosis factor alpha." (PMID 37755304, 2023). "For instance, the combination of the diphtheria toxin and TNF-alpha exhibited synergistic cytotoxicity effects in sensitive and resistant human ovarian tumor cell lines including SKOV-3 cells." (PMID 37242538, 2023). "In conclusion, our studies show that NCX4040 treatment of ovarian tumor cells results in the differential induction of oxidative stress genes, inflammatory response genes (TNF, IL-1, IL-6 and COX2), DNA damage response and MAP kinase response genes." (PMID 36612280, 2022). "TNFα was shown to be significantly upregulated in ovarian tumor tissues, leading to NF-κB activation." (PMID 34638514, 2021). "It is well-known that pro-inflammatory cytokines, particularly IL-1β, IL-6 or TNF-α, promote ovarian tumor growth and metastasis, and their high serum levels are correlated with poor clinical outcomes." (PMID 34771587, 2021). "In contrast, another study demonstrated that, in mice and patients, chronic production of TNF-α in ovarian tumors promotes IL-17 production by TH17, leading to myeloid cell recruitment, which in turn participate in tumor progression." (PMID 32630708, 2020). "A previous study showed that paclitaxel induces ovarian tumor cell apoptosis via the TNF-induced ERK/Akt signaling pathway." (PMID 33256016, 2020). "The synergistic activity of DTA and TNFα on ovarian tumor cell lines and nude mice ovarian cancer models has also investigated." (PMID 31681205, 2019). "We also observed that a variety of structurally distinct chemotherapy drugs with distinct mechanisms of action induce TNF-α release from breast and ovarian tumor cell lines with similar kinetics." (PMID 28915246, 2017). "In our study, we observed that despite the increased basal output of TNF-α from both breast and ovarian tumor cell lines during acquisition of docetaxel resistance, there was a diminished ability to further increase TNF-α production in response to docetaxel." (PMID 28915246, 2017). "Recently, it has been shown in vitro that TNF-α is released by breast and ovarian tumor cells in response to taxane exposure." (PMID 28915246, 2017). "The production of acute-phase proteins is generated by different stimuli involving cytokines (TNF, IL-1, and IL-6), which are secreted by ovarian tumor cells in vitro and in vivo." (PMID 25183900, 2014). "In our study, we showed for the first time that docetaxel (at concentrations between 3 and 45 nM) can stimulate TNF-α production and sTNF-α release from both breast and ovarian tumor cells." (PMID 22225778, 2012). "Moreover, ovarian tumor cells are known to secrete large amounts of TNF-α into the tumor microenvironment." (PMID 37305383, 2023). "Furthermore, NCX4040 treatment induced TNF-dependent pathways which further increases oxidative stress in ovarian tumor cells, resulting in enhanced NCX4040-mediated cell death from apoptosis and/or ferroptosis." (PMID 36612280, 2022). "Furthermore, NCX4040 treatment also induced TNF-dependent pathways which further increases oxidative stress in ovarian tumor cells, resulting in enhanced NCX4040-mediated cell death from apoptosis and/or ferroptosis." (PMID 36612280, 2022).
ovarian tumor (continued). "Once formed, pro-tumoral TAMs affect the ovarian tumor microenvironment by the secretion of anti-inflammatory cytokines, such as IL-4, -5, -6, -10, as well as tumor necrosis factor α (TNF- α) and TGF-β, altogether impairing the activity of other immune cells in the tumor microenvironment." (PMID 34638494, 2021). "Furthermore, TNF-α, secreted by pro-inflammatory macrophages, enhances the metastatic potential of ovarian tumor cells via activation of the NF-κB signaling pathway." (PMID 32670264, 2020). "The increase in TNF-alpha level results from activation of immune response to ovarian tumor." (PMID 28376925, 2017). "M-CSF, known as a colony stimulating factor 1 (CSF-1), is also a potent chemoattractant for monocytes, which in turn, can produce factors that stimulate proliferation of ovarian tumor cells including interleukin-1 (IL-1), interleukin-6 (IL-6) and tumor necrosis factor (TNF)." (PMID 25935153, 2015). "Therefore, we speculated here, that the increased levels of the pro-inflammatory cytokines, IL-1β, IL-6 and TNF-α in tumor-bearing mice is dependent on the production of TNF-α by ovarian tumor cells." (PMID 37305383, 2023). "Additionally, scavenger receptor expression is also reduced in TAM from ovarian tumors treated with TNF-α antibodies or developed in TNF-α(−/−) mice, indicating chemical communication between cancer cells and macrophages as an important factor in regulating the local microenvironment." (PMID 28929459, 2018). "In addition, ovarian tumors acquire aberrant NF-κB functions allowing them to circumvent apoptotic pathways, specifically tumor necrosis factor alpha- (TNFα)-induced apoptosis, and afford protection against environmental insults such as anti-tumor immune effectors or chemotherapy." (PMID 19500386, 2009). "In this study, we provide evidence that NCX4040 induces the differential induction of oxidative stress genes, inflammatory response genes (TNF, IL-1, IL-6 and COX2), DNA damage response and MAP kinase response genes in human ovarian tumor cells." (PMID 36612280, 2022). "Microarray analysis also identified pathways related to TNFα and MAPK in these ovarian tumor cells following NCX4040 treatment." (PMID 36612280, 2022). "A similar trend was observed for cytokines TNF-α and CXCL1 when A2780 ovarian tumor cells were selected for docetaxel resistance." (PMID 28915246, 2017). "We speculate that it would be beneficial for patients with EGFR+ ovarian tumors that secrete TNFα to consider a combination regime of anti-EGFR mAb, like cetuximab, and TNFα blocking agents." (PMID 33540543, 2021). "In vitro stimulation assays similarly revealed that the CE7R+ T cells produced significant amounts of pro-inflammatory cytokines such as IFN-γ and TNF-α upon co-culture with all L1-CAM+ ovarian tumor cell lines, but not upon stimulation with the L1-CAM-negative A2780 cells." (PMID 26761817, 2016).
spondylitis (30 papers, 2007 to 2026). The inflammation of a vertebra. "In this study, TNF blockade resulted in a significant reduction in the severity of spondylitis associated with a significant reduction of axial inflammation and bone roughness at the level of the caudal spine." (PMID 35055042, 2022). "In our study dual anti-TNF and anti-IL-17A therapy resulted in significant reduction of spondylitis and swelling at the level of the peripheral joints." (PMID 35055042, 2022). "Both single therapies as well as TNF and IL-17A dual blockade therapy reduced clinical spondylitis and peripheral arthritis effectively and similarly." (PMID 35055042, 2022). "Correlation between DNA methylation of SOCS1 and the degree of inflammation, assessed by TNFα and IL-6 levels, was also shown in patients with HLA-B27+ spondylitis." (PMID 32670294, 2020). "In contrast, TNF blockage in AS patients is an effective therapeutic approach able to show improvement of disease activity in 60% of patients with active spondylitis." (PMID 26125554, 2015). "Functional severity (Bath Ankylosing Spondylitis Functional Index) and radiographic severity (modified Stoke Ankylosing Spondylitis Spine Score) were also worse in those who received TNFα inhibitor therapy (P < 0.0001 for both variables)." (PMID 24755322, 2014). "Blockade of DKK-1 has also been shown to drive ankylosis in a TNF-over-expressing mouse model of spondylitis." (PMID 23171658, 2012). "The radiologic response of patients with AS to TNF-α inhibitors can be measured using the Ankylosing Spondylitis spine Magnetic Resonance Imaging-activity (ASspiMRI-a) system, the Berlin modification of ASspiMRI-a and of the Spondyloarthritis Research Consortium of Canada (SPARCC) scoring system." (PMID 26176701, 2015). "Indeed, in this study and in others, it has been shown that spondylitis may still be present after 2 years of anti-TNF therapy – even in patients with definite clinical improvement." (PMID 18761747, 2008). "Clinical activity was assessed by the Ankylosing Spondylitis Disease Activity Score (ASDAS) at baseline (at the beginning of the first and second anti-TNF therapy) and at 6 months after switching." (PMID 23890223, 2013). "High SOST levels occur in hTNFtg mice, as TNF-α stimulates SOST expression but if the mice are treated with Dikkopf-1 neutralising antibodies, which also results in reduced levels of SOST, spondylitis occurs." (PMID 26612313, 2015). "Clinically, various anti-TNF therapies suppress the inflammation process but do not retard the structural progression according to modified Stoke's Ankylosing Spondylitis Spinal Score (mSASSS)." (PMID 22632381, 2012). "In line with this, the Groningen Leeuwarden Ankylosing Spondylitis (GLAS) cohort, after a 52-week follow-up period, found a correlation between higher NSAID intake and increased ASDAS, regardless of the use of TNF-inhibitors." (PMID 38966536, 2024).
acute lymphoblastic leukemia (29 papers, 2012 to 2025). Leukemia with an acute onset, characterized by the presence of lymphoblasts in the bone marrow and the peripheral blood. "In this study, we evaluated the frequency of TNF–α rs1800629 (–308 G>A) polymorphism in newly diagnosed adult patients with acute lymphoblastic leukemia (ALL) and its correlation with age at diagnosis, gender and subtype of ALL." (PMID 35886021, 2022). "In acute lymphoblastic leukemia cell lines Jurkat and Molt-4, the potential of pterostilbene to modulate Fas, a member of the death-inducing family of tumor necrosis factor (TNF), was investigated." (PMID 32085381, 2020). "EV derived from the acute lymphoblastic leukemia (CCRF) cells modify the actions of the proinflammatory cytokine TNF in U937 cells, resulting in antagonistic, additive or synergistic effects." (PMID 29434584, 2018). "Human acute lymphoblastic leukemia (ALL) cells resisted SM treatment under isotonic conditions due to poor SM-induced TNF secretion." (PMID 28771230, 2017). "Hypertonicity allowed robust TNF-dependent killing in SM-treated human acute lymphoblastic leukemia cells, which under isotonic conditions resisted SM treatment due to poor SM-induced TNF secretion." (PMID 28771230, 2017). "ALB and TNF may serve as potential biomarkers for the diagnosis and treatment of acute lymphoblastic leukemia in children with MLL gene rearrangements." (PMID 41293238, 2025). "We have previously shown that FAB subgroups M4 and M5 are characterized by the highest LDL degradation rate compared to FAB-M1-3 and acute lymphoblastic leukemia which is in agreement with reports showing that TNF-α, IL-6, IL-8, and IL-18 are over-expressed and secreted in these subgroups." (PMID 28488049, 2017). "Furthermore, the genes encoding IFN-γ, GM-CSF, IL-4, IL-8, IL-2Rα, IL-2Rβ, IL-4R, IL-12Rβ, chemokines, chemokine receptors, and TNF were highly expressed in CIK cells under stimulation by acute lymphoblastic leukemia (ALL) cells." (PMID 25962508, 2015). "Tumor necrosis factor α (TNFα)-mediated ROS generation can inhibit DUSP enzymes, so it is possible to induce that pathway by BCI especially since its cytotoxicity in pre-B acute lymphoblastic leukemia cells was decreased in the presence of free radical scavengers." (PMID 37760412, 2023). "Indeed, GB elicited an increase of TNF-α production, caspase-8 and caspase-3 activation, and PARP-1 cleavage within pre-B acute lymphoblastic leukemia Nalm-6 cells." (PMID 24039967, 2013). "This study examined the impact of TNFα (G308A) and IL10 (G1082A) polymorphisms at promoter regions in relation to the overall survival of 105 children (0 ≤ 18 years) with acute lymphoblastic leukemia (ALL) for a period of 126 months, treated according to the protocol GBTLI99." (PMID 23213548, 2012). "In addition, baicalin reduced the survival of peripheral blood leukocytes (PBLs) in individuals suffering from acute lymphoblastic leukemia (ALL), increased IFNγ production in PBLs and decreased the production of TNFα and IL-10 in bone marrow cells (BMCs) in ALL patients." (PMID 39911847, 2025). "However, in contrast to stable CD80 and/or CD86 expression on primary DLBCL cells, PD-L1 cell surface expression on pediatric B-cell precursor acute lymphoblastic leukemia (ALL) depends on induction by IFN-γ and TNF-α." (PMID 38340727, 2024). "According to the previous reports, GSK-J4 inhibits lipopolysaccharide-induced TNFα production in human primary macrophages with IC50 of 9 μM21 and blocks growth of T cell acute lymphoblastic leukemia (T-ALL) cells with IC50 of 2 μM, indicating that GSK-J4 is a highly potent inducer of ATF4 and CHOP." (PMID 33633164, 2021).
chronic gastritis (29 papers, 2012 to 2025). Inflammation of the stomach that is chronic in nature. "H. pylori infection causes chronic gastritis and induces an inflammatory response that increases the pro-inflammatory factors interleukins (IL-1β, IL-6, IL-8, IL-17), tumour necrosis factor α (TNF-α), interferon γ (IFN-γ), and C-reactive protein (CRP)." (PMID 38475712, 2024). "Regarding TNF-α -238 G/A polymorphism, the frequency of TNF-α -238 A allele and TNF-α-238 GA/AA genotypes were observed lower in patients with PL and GC compared to chronic gastritis and HC." (PMID 32592356, 2020). "Regarding TNF-α promoter -238 G/A locus, the frequency of A allele is 17% in HC and it was observed in decline together with the increase of gastric lesions severity, in the following order: 10.7% in chronic gastritis, 4% in PL and 3.5% in GC." (PMID 32592356, 2020). "Regarding TNF-α promoter -308 G/A locus, the frequency of A allele is 8% in HC and has shown an increase with the severity of gastric lesions, with the following order: 10.8% in chronic gastritis, 21% in PL and 27.5% in GC." (PMID 32592356, 2020). "H. pylori infection causes chronic gastritis and induces a permanent inflammatory response that may increase both the gastric and the systemic indexes of inflammation, such as TNF-α, IL-1, and IL-6." (PMID 29743888, 2018). "In DGC, Helicobacter pylori infection plays a central etiological role, initiating chronic gastritis and promoting an inflammatory milieu characterized by cytokines such as IL-1β, TNF-α, and IL-8, which contribute to mucosal damage and carcinogenesis." (PMID 40862793, 2025). "H. pylori is a well-established pathogen in chronic gastritis, capable of inducing long-term inflammatory responses through the release of pro-inflammatory mediators such as tumor necrosis factor-alpha (TNF-α) and interleukin-1 (IL-1)." (PMID 41003013, 2025). "Prolonged H. pylori infection is thought to lead to chronic gastritis, where gastric acid secretion is inhibited by inflammatory mediators such as tumor necrosis factor-α (TNF-α) and interleukins." (PMID 36209270, 2022). "TNF-α serum levels in the GC group were higher than those recorded in patients with PL and patients with chronic gastritis compared to HC." (PMID 32592356, 2020). "TNF-α serum levels mean were as follows 36 pg/ml in HC, 50.7 pg/ml in chronic gastritis, 55 pg/ml in PL, and 116.6 pg/ml in GC." (PMID 32592356, 2020). "We remarked that TNF-α serum levels increase among patients with chronic gastritis, with PL and mainly in those suffering from GC." (PMID 32592356, 2020). "Most patients with H. pylori infection will develop chronic gastritis, which induces inflammatory cytokines, such as interleukin 1 (IL-1) and tumor necrosis factor alpha (TNF-α)." (PMID 28388631, 2017). "Expression of serum cytokines (IL-17A, IL-21, IL-23, IL-10, and TNF-α) in H. pylori-infected patients was compared with healthy controls and correlated with disease severity (mild chronic gastritis, moderate chronic gastritis, and severe chronic gastritis)." (PMID 29391865, 2017). "H. pylori infection results in increased expression of TNFA, IL6, IL12A and IL2 in the gastric mucosa, in addition to the effect of chronic gastritis, and for TNF‐α and IL‐2 proteins, this increase was mainly observed in inflammatory cells." (PMID 26945693, 2016). "The KEGG enrichment analysis indicated that the TNF signaling pathway may be involved in the regulation of chronic gastritis tissues, while the GO enrichment pathways were mainly some ionic pathways." (PMID 40283972, 2025). "In addition, they observed significantly higher levels of TNF-α in the active chronic and chronic gastritis patients as compared to the uninfected groups." (PMID 36057049, 2022). "In addition, increased production of IL-6 and TNF-α in human antral mucosa cultures from H. pylori-infected chronic gastritis patients has been observed by others." (PMID 31065302, 2019).